BTD (biotinidase)
Description:
Catalytic release of biotin from biocytin, the product of biotin-dependent carboxylases degradation.
Tractability: Small molecule: a high-quality ligand is known. Antibody: UniProt places it where antibodies can reach, with high confidence; its Gene Ontology location is reachable by antibodies, with high confidence; UniProt predicts a signal peptide or a membrane-spanning region. PROTAC: ubiquitination databases record sites on it; its protein half-life has been measured; a small molecule that binds it is known.
Target class: Enzyme; Hydrolase
Gene: Protein-coding gene on chromosome 3 (15,601,341 to 15,722,311, forward strand). Ensembl gene ENSG00000169814.
Subcellular location: Secreted, extracellular space
Pathways (Reactome):
Disease: Defective BTD causes biotidinase deficiency
Metabolism: Biotin transport and metabolism
Gene Ontology:
Molecular function: protein binding; biotinidase activity; hydrolase activity, acting on carbon-nitrogen (but not peptide) bonds, in linear amides
Biological process: biotin metabolic process; central nervous system development
Cellular component: extracellular exosome; extracellular region; mitochondrial matrix
Genetic constraint (gnomAD): Loss-of-function variants: 15 observed, 18.93 expected, observed/expected ratio (o/e) 0.79, 90% interval 0.53 to 1.22. The upper end of that interval is the gene's LOEUF score, 1.22, which puts it in group 5 of 6, group 1 being the genes least tolerant of losing a copy. Missense variants: 671 observed, 682.64 expected, observed/expected ratio (o/e) 0.98, 90% interval 0.92 to 1.05. Synonymous variants: 240 observed, 259.04 expected, observed/expected ratio (o/e) 0.93, 90% interval 0.83 to 1.03.
Gene-disease validity (ClinGen):
ClinGen rates the evidence that BTD causes each of these diseases.
biotinidase deficiency (autosomal recessive): Definitive. A late-onset form of multiple carboxylase deficiency, an inborn error of biotin metabolism that, if untreated, is characterized by seizures, breathing difficulties, hypotonia, skin rash, alopecia, hearing loss and delayed development.
Leigh syndrome (autosomal recessive): Moderate. A progressive neurological disease defined by specific neuropathological features associating brainstem and basal ganglia lesions.
Homologues: Orthologues: chimpanzee BTD (99% identical), macaque BTD (96% identical), dog BTD (85% identical), mouse Btd (84% identical), guinea pig BTD (83% identical), rat Btd (80% identical), pig BTD (78% identical), rabbit BTD (71% identical), tropical clawed frog btd (56% identical), zebrafish btd (47% identical), Drosophila melanogaster vanin-like (26% identical), Drosophila melanogaster CG32751 (26% identical), and 2 more. Paralogues in human: VNN1 (39% identical), VNN2 (37% identical).
Diseases named in the same sentence as BTD in open-access papers:
BTD is named in the same sentence as 98 diseases in open-access papers, as found by Europe PMC text mining. Sharing a sentence is not in itself a finding about the gene and the disease. The quoted sentences say what the papers report.
biotinidase deficiency (21 papers, 2014 to 2026). "Another example is the rs13078881 variant in the BTD gene, linked to biotinidase deficiency (OMIM*609019; ICD‐11 4B4Y), a vitamin metabolism disorder." (PMID 40763936, 2026). "Biotinidase deficiency is a rare treatable metabolic disorder caused by biallelic mutations in the BTD gene." (PMID 40171223, 2025). "Biotinidase deficiency (BTD) is a rare autosomal recessive metabolic disorder characterized by either a complete or partial deficiency of the enzyme biotinidase (BT), which is essential for recycling biotin." (PMID 40062096, 2025). "Biotinidase deficiency (BD) is a rare autosomal recessive neurometabolic disorder associated with mutations in the BTD gene." (PMID 40171223, 2025). "BTD gene, associated with biotinidase deficiency, showed a high carrier frequency (1:16) in our cohort, compared to Non-Finnish European (NFE) population (1:25)." (PMID 41303398, 2025). "Biotinidase deficiency is an autosomal recessiveinherited metabolic disorder that is caused by the biotinidase enzyme(EC 3.5.2.12) deficiency in the release and recycling of endogenousbiotin from biocytin and short biotinyl peptides." (PMID 37901531, 2023). "In this study, the DICmethod was successfully applied to patientswith different ages and biotinidase levels, including newborn screening,to adults with a positive correlation to the colorimetric method.Biotinidase deficiency is a treatable disease." (PMID 37901531, 2023). "Biotinidase deficiency is a form of multiple carboxylase deficiency caused by homozygous/compound heterozygous mutations in the BTD gene (609019) on chromosome 3p25 composed of 4 exons and 3 introns." (PMID 35627187, 2022). "Biotinidase deficiency (BD) is an autosomal recessive inherited disorder in which the enzyme biotinidase is totally or partially defective and the vitamin biotin is not recycled." (PMID 35805799, 2022). "Genetic testing of the BTD gene revealed compound heterozygosity for pathogenic variants (p.Gly36Ser, p.Cys425Arg), thereby confirming the diagnosis of biotinidase deficiency (MIM: 253260)." (PMID 35606766, 2022). "Diagnosis of biotinidase deficiency can be confirmed enzymatically by measuring biotinidase enzyme activity or molecularly by identifying mutations in the BTD gene which encodes the biotinidase enzyme." (PMID 34295297, 2021). "Biotinidase deficiency is an inherited autosomal recessive disorder where the biotinidase enzyme activity is blocked, resulting in the inability to release biotin from the diet and recycling this vitamin." (PMID 31973013, 2020). "Biotinidase deficiency is an autosomal recessive metabolic disorder whose diagnosis currently depends on clinical symptoms and a biotinidase enzyme assay." (PMID 31973013, 2020). "The diagnosis of biotinidase deficiency is established by analyzing serum levels of the biotinidase enzyme and the BTD gene." (PMID 33520891, 2020). "HFE rs1800562 causing hereditary hemochromatosis presented the highest frequency (7.54%), followed by BTD rs13078881 for biotinidase deficiency (7.08%), FLG rs61816761 for ichthyosis vulgaris and atopic dermatitis (3.38%), and FANCM rs147021911 for Fanconi anemia (3.08%)." (PMID 40763936, 2026). "Biotinidase deficiency is associated with the BTD gene, which is an autosomal recessive disorder." (PMID 38592052, 2024). "Mutations in the BTD gene cause Biotinidase deficiency, a treatable deficiency in biotin that may have an immunodeficiency component." (PMID 36860866, 2023). "However, given the reduced biotinidase activity, which corresponds to a diagnosis of partial biotinidase deficiency, the proband was classified as BTD affected with BTD deficiency." (PMID 35627187, 2022). "The development of new algorithms and programs examining these mechanisms and pathways of the central nervous system and immune system may better explain the role of biotinidase and the pathogenesis of biotinidase deficiency." (PMID 27752475, 2016).
biotinidase deficiency (continued). "However, with the development of new algorithms and programs examining various mechanisms and pathways in the central nervous system, these analyses may help us to understand better the role of biotinidase and the pathogenesis of biotinidase deficiency." (PMID 27752475, 2016). "Biotinidase deficiency (BD) is an autosomal recessive metabolic disorder that affects the BTD gene; this gene is responsible for producing an enzyme called biotinidase (Online Mendelian Inheritance in Man (OMIM), 2023)." (PMID 40498416, 2025). "Biotinidase deficiency (BD) is an autosomal recessive disorder caused by mutations in the BTD gene, resulting in reduced or absent BTD activity, impairing biotin recycling." (PMID 41007772, 2025). "Biotinidase deficiency (BD) (OMIM # 253260) is a rare (one in 60,000 births) AR MD attributed to pathogenic variants in the BTD gene (chromosome 3p25.1), responsible for encoding the biotinidase enzyme." (PMID 40085371, 2025). "The patients who are homozygous for the p.Asp444His pathogenic variant are expected to have serum biotinidase enzyme activity consistent with partial BTD deficiency, and thus may not require biotin therapy and should only be monitored or—if treated—low doses of biotin are recommended." (PMID 35627187, 2022).
multiple carboxylase deficiency (8 papers, 2013 to 2025). "Mutations in the genes encoding biotinidase (BTD) or holocarboxylase (HLCS) synthetase can lead to Multiple Carboxylase Deficiency (MCD)." (PMID 38735926, 2024). "Both enzymes (biotinidase and holocarboxylase synthase) are involved in the biotin cycle required for precise holocarboxylase formation, while deficiencies of both enzymes are genetic causes of multiple carboxylase deficiency." (PMID 34940649, 2021). "Multiple carboxylase deficiency (MCD) can either be due to biotinidase or holocarboxylase synthetase deficiencies." (PMID 37759536, 2023). "Multiple carboxylase deficiency (MCD, MIM: 253270), a common heritable organic acidaemia, is caused by defects in either biotinidase or holocarboxylase synthetase (HLCS, EC 6.3.4.10)." (PMID 41029453, 2025).
cystic fibrosis (5 papers, 2013 to 2024). Autosomal recessive disorder caused by pathogenic variants in the CFTR gene (cystic fibrosis transmembrane conductance regulator), which encodes a chloride and bicarbonate channel expressed in epithelial cells, and follow the diagnosis criteria. "Infants are also investigated for galactosemia, cystic fibrosis, biotinidase deficiency, glucose-6-phosphate dehydrogenase (G6PD) deficiency, congenital adrenal hyperplasia (CAH), and amino acid abnormalities." (PMID 38832201, 2024). "For example, in New Zealand, galactosemia, congenital adrenal hyperplasia, biotinidase deficiency, cystic fibrosis and maple syrup urine disease were successively added to the list of screening conditions, over the 1970s and 1980s." (PMID 23055099, 2013). "In addition, diseases such as Cystic Fibrosis (OMIM# 219700), Phenylketonuria (OMIM# 261600) and Biotinidase Deficiency (OMIM# 253260) have also been reported in a number of families." (PMID 37214420, 2023). "Specifically, despite being reliable for hemoglobinopathies, GALT and biotinidase enzymes as well as providing baseline testing for amino acids and acylcarnitines, admission testing may result in inaccurate TSH, 17-OHP, and cystic fibrosis (IRT) screening." (PMID 27057333, 2015).
galactosemia (5 papers, 2020 to 2025). "The current screening panel of 83 disorders performed by the Laboratory includes Galactosemia, Biotinidase Deficiency, Congenital Hypothyroidism, Congenital Adrenal Hyperplasia, 25 Amino Acid Disorders, 16 Fatty Acid Oxidation Disorders, 25 Organic Acidemias, and 12 Hemoglobinopathies." (PMID 33073010, 2020). "All biotinidase deficiency patients exhibited likely pathogenic mutations in the BTD gene, while missense mutations were found in galactosemia patients." (PMID 36468010, 2022). "The assay for classic galactosemia, by the measurement of the activity of galactose-1-phosphate uridyl transferase had the smallest reduction (<23%) and the requests for the investigation of biotinidase increased by 11%." (PMID 34927665, 2021). "In India, it is recommended to include screening programs for treatable disorders like CH, CAH, G6PD, galactosemia (GALT), biotinidase, CF, and hemoglobinopathy variations such as sickle cell disease in target populations." (PMID 38832201, 2024).
epilepsy (4 papers, 2019 to 2025). A brain disorder characterized by episodes of abnormally increased neuronal discharge resulting in transient episodes of sensory or motor neurological dysfunction, or psychic dysfunction. "DLG2 belongs to the gene motif “BGNADP”, which is a network associated with ID and epilepsy, including also BTD, GALNT10, NMUR2, AUTS2, and PTPRD." (PMID 35627244, 2022). "For instance, rare or low-frequency variants causing rare diseases such as hearing impairment, corneal dystrophy, Stargardt disease, epilepsy, biotinidase, and butyrylcholinesterase deficiencies were identified in South Asian populations (GIH, ITU, PJL, and STU)." (PMID 40136566, 2025). "Biotinidase enzyme activity measurements of patients' sera of diabetes mellitus type 1, epilepsy patients on ketogenic diet and GSD Ia patients were performed as part of routine blood testing." (PMID 33473341, 2021). "Additionally, a group of epilepsy patients (n = 4), who were on a ketogenic diet as part of the antiepileptic treatment regime, showed an increase in BTD enzyme activity to 12.1 nmol/min/mL with SD of 2.1." (PMID 33473341, 2021).
alopecia (3 papers, 2013 to 2025). Hair loss usually from the scalp. "In the absence of normal biotinidase activity, babies tend to develop primary neurologic symptoms such as seizures, hypotonia, vision problems and hearing loss, along with cutaneous abnormalities, including skin rashes, alopecia and recurrent viral or fungal infections." (PMID 40498416, 2025).
Hypoglycemia (3 papers, 2017 to 2024). A decreased concentration of glucose in the blood. "A likely pathogenic variant was identified in the BTD gene in family 1, which was found to be relevant to the patient’s phenotype, including hypertonia and hypoglycemia." (PMID 38592052, 2024). "In a patient diagnosed with partial biotinidase deficiency and genotype p.Cys33PhefsTer36/p.Asp444His, recurrent hypoglycemia (atypical sign in BD) and metabolic acidosis at 19 years of age have been reported." (PMID 35627187, 2022).
breast carcinoma (2 papers, 2010 to 2012). "A blinded set of plasmas from 21 breast cancer patients (age = 36 - 78, cancer grade = O - IV) and 21 normal healthy women (age = 17 - 49) were tested to determine individual levels of BTD and GPX3 by Western blots." (PMID 20346108, 2010). "In this study we discovered serum BTD as a potential breast cancer biomarker through the biomarker development pipeline encompassing mass spectrometry based screening and independent downstream immunoblot assays." (PMID 20346108, 2010). "Despite many uncertainties in the cellular and molecular mechanism of BTD, it is apparent from our results that BTD is down-regulated in breast cancer plasma." (PMID 20346108, 2010). "Consistent with the preliminary data, significant down-regulation of BTD was observed in breast cancer plasma compared to the normal healthy control (p = 0.002)." (PMID 20346108, 2010). "The employed ICAT and Western blot assay strategy enabled us to identify and quantify biotinidase (BTD) as a potential breast cancer biomarker in plasma." (PMID 20346108, 2010). "So, it merits further studies to elucidate down-regulation of BTD in relation to the behavior of breast cancer cells." (PMID 20346108, 2010). "Interestingly, the mRNA level of BTD in breast cancer tissue also changed compared to normal breast tissues." (PMID 20346108, 2010). "Interestingly, transcriptional levels of BTD in breast cancer tissues were also down-regulated." (PMID 20346108, 2010). "The two candidates, BTD and GPX3, confirmed by this approach were next tested with immunoblot assay in a blinded set of breast cancer and control to ascertain the markers ability to differentiate the two groups." (PMID 20346108, 2010). "In the initial stages of biomarker discovery using ICAT and Western blot analysis, we confidently observed that BTD and GPX3 were significantly down-regulated in breast cancer plasma compared to age-matched normal healthy control." (PMID 20346108, 2010).
deficiencies (2 papers, 2010 to 2018). "In another study, there was an association with serum biotinidase and Acetyl carnitine deficiencies." (PMID 30364427, 2018). "Interestingly, higher circulating concentrations of 2-HB are associated with perturbation in biotin metabolism, specifically in inherited biotinidase deficiencies, and poor biotin status has been associated with insulin resistant states (and references therein)." (PMID 21170321, 2010).
glycogen storage diseases (2 papers, 2021 to 2025). "Plasma biotinidase activity, known to be elevated in patients with hepatic glycogen storage diseases, was 80% of normal mean." (PMID 34828390, 2021).
HLCS deficiency (2 papers, 2020 to 2021). "Some examples of success in our programme include the screening for biotinidase and HLCS deficiency." (PMID 34449524, 2021). "In this paper, we report a Chinese Han pedigree with HLCS deficiency diagnosed by using next-generation sequencing and validated with Sanger sequencing of the HLCS and BTD genes." (PMID 32727382, 2020).
Hyperammonemia (2 papers, 2014 to 2022). An increased concentration of ammonia in the blood. "Therefore, when BTD is deficient, the metabolic abnormalities associated with these three critical substances, such as organic aciduria, hyperammonemia, and secondary ketoacidosis, will occur." (PMID 35745003, 2022).
lactic acidosis (2 papers, 2022 to 2025). Metabolic acidosis characterized by the accumulation of lactate in the body. "Differential diagnoses to consider in infants presenting with severe lactic acidosis include biotinidase deficiency, pyruvate dehydrogenase complex deficiency, respiratory chain disorder, TCA disorders, carbonic Anhydrase VA Deficiency, and gluconeogenic defects." (PMID 36348915, 2022). "Biotin and/or thiamine were used more frequently in neonatal lactic acidosis or acute Leigh syndrome, to treat the possibility of deficiency of the SLC19A3 thiamine transporter, biotinidase or pyruvate dehydrogenase complex." (PMID 39529390, 2025).
neuromyelitis optica (2 papers, 2021 to 2025). A rare inflammatory disease of the central nervous system characterized mainly by attacks of uni- or bilateral optic neuritis (ON) and acute myelitis. "In conclusion, biotinidase deficiency is a rare and treatable cause of neuromyelitis optica." (PMID 35265569, 2021). "Biotinidase enzyme levels should be considered as part of the examination algorithm for neuromyelitis optica spectrum disorder." (PMID 35265569, 2021). "Children who present with neuromyelitis optica with negative AQP4-Abs should be evaluated for biotinidase deficiency." (PMID 35265569, 2021).
Alexander disease (1 paper, 2024). Alexander disease (AxD) is a rare neurodegenerative disorder of the astrocytes comprised of two clinical forms: AxD Type I and Type II manifesting with various degrees of macrocephaly, spasticity, ataxia and seizures and leading to psychomotor regression and death. "This group is presented by vitamin B12, vitamin E, copper or biotinidase deficiencies, Leber's hereditary optic neuropathy, and leukodystrophies (including Alexander's disease)." (PMID 39781148, 2024).
autoimmune encephalitis (1 paper, 2025). Inflammation of the brain secondary to an immune response triggered by the body itself. "A genetic test for autoimmune encephalitis in a commercial lab was negative, as was a biotinidase deficiency test." (PMID 40565278, 2025).
biotin deficiency (1 paper, 2016). "Not only does this scenario compare developmental gene changes from Day 1 to Day 8, but also genes that are up- and down-regulated in response to the stresses of biotinidase deficiency and consequential biotin deficiency." (PMID 27752475, 2016).
Brain atrophy (1 paper, 2016). Partial or complete wasting (loss) of brain tissue that was once present. "Brain atrophy was seen in our patients with biotinidase deficiency." (PMID 27375759, 2016).
cervical cancer (1 paper, 2018). A primary or metastatic malignant neoplasm involving the cervix. "Notably, PEG3, SPON1, BTD and RPLP2 passed the defined threshold of FDR <0.25, indicating the potential of these genes in showing their significances in cervical cancer." (PMID 30065881, 2018).
diabetes mellitus type 1 (1 paper, 2021). "Future studies aiming at confirming this hypothesis should involve a higher number of samples and could eventually expand the spectrum of BTD enzyme activity as a biomarker beyond GSDs to detect perturbed gluconeogenesis and lipogenesis, such as in diabetes mellitus." (PMID 33473341, 2021).